NLRP3 (NLR family pyrin domain containing 3)
Diseases named in the same sentence as NLRP3 in open-access papers (continued):
Sharing a sentence is not in itself a finding about the gene and the disease.
pericarditis (continued). "Together, these data validate the role of the NLRP3 inflammasome and IL-1 in pericarditis." (PMID 40079000, 2025). "This pathway may explain colchicine’s efficacy in treating FMF and recurrent pericarditis, as it inhibits the self-assembly of cytoskeleton microtubules and reduces NLRP3-dependent IL-1β release." (PMID 39458001, 2024). "The expression of NLRP3 and caspase-1 were also observed significantly upregulated in pericarditis cases vs. controls, which echoed the hypothesis from pharmaceutical treatments, emphasizing the essence of the development in pericarditis." (PMID 36204568, 2022). "These clues hint the NLRP3 inflammasome/IL-1 signal pathway may play a central role in the process of pericarditis." (PMID 36204568, 2022). "A recent study showed that NLRP3 (nucleotide-binding oligomerization domain-like receptor protein 3) inflammasome activation, responsible for interleukin 1 release, may be incriminated in the development of pericarditis." (PMID 40943703, 2025). "Although all pharmacological agents tested could alleviate inflammation tosome extent, drugs directly or indirectly targeting the NLRP3 inflammasomepathway (i.e., colchicine, 16673-34-0, anakinra, and IL-1 trap) were able toattenuate the pathological changes occurring after acute pericarditis." (PMID 39077487, 2023). "Confirming its involvement in pericarditis, Mauro’s group reported the presence of NLRP3, ASC and caspase-1 expression in pericardial biopsies from pericarditis patients." (PMID 41272654, 2025). "Colchicine, a non-selective NLRP3 inflammatory vesicle inhibitor, has established efficacy in the treatment of pericarditis and is regarded as a standard of care." (PMID 39022620, 2024). "However, no clear evidence for the role of NLRP3 in radiation-induced pericarditis has been reported, while an involvement of NLRP3 in the pathogenesis of pericarditis has been assumed in recent years." (PMID 41272654, 2025).
prostate carcinoma (23 papers, 2016 to 2025). A carcinoma that arises from epithelial cells of the prostate gland. "To further understand the role of inflammasomes in prostate cancer, we analyzed the protein expression of inflammasome sensors NLRP3 and NLRP12, and its associated proteins ASC and pro-caspase-1." (PMID 28663562, 2017). "Moreover, the NLRP3 inflammasome has been implicated in promoting prostate islet damage, indicating its potential involvement in the pathophysiology of prostate cancer." (PMID 39769450, 2024). "Thus, a few studies indicate that activation of the NLRP3 inflammasome has been associated with promoting inflammation-induced carcinogenesis in prostate cancer." (PMID 39769450, 2024). "Similarly, Natriuretic peptides such as Atrial Natriuretic Peptides (ANPs) and B-Type Natriuretic Peptide (BNP) have been found to inhibit NLRP3 inflammasome and its associated inflammatory response in prostate cancer." (PMID 39769450, 2024). "Because hypoxia in prostatic tumors is associated with chronic inflammation and a poor outcome for prostate cancer patients, we investigated whether hypoxia in human PrECs, prostate cancer and myeloid cell lines promotes NLRP3 and AIM2 inflammasome activation." (PMID 27058421, 2016). "Similarly, NLRP3 has been associated with tumor–node–metastasis staging in prostate cancer." (PMID 39769450, 2024). "NLRP3-related genes are upregulated in prostate cancer, with NLRP3 inflammasome protein overexpressed; this overexpression correlates with clinical parameters such as cancer staging and lymph node infiltration." (PMID 40718836, 2025). "Ulinastatin improves the malignant progression of prostate cancer cells by blocking the RhoA/ROCK/NLRP3 pathway." (PMID 40718836, 2025). "Research on the role of the NLRP3 inflammasome in prostate cancer progression has increased in recent years, primarily focusing on its promoting effects, although findings remain contradictory, indicating the need for further investigation." (PMID 40718836, 2025). "Further, they have shown that activation of NLRP3 mediates prostate cancer cell proliferation and migration, and inhibition of NLRP3 prevents it." (PMID 39769450, 2024). "Further, expression of NLRP3 in prostate cancer cells (PC-3) has been shown to be increased under hypoxia." (PMID 39769450, 2024). "Although few studies indicate the beneficial role of NLRP3 inflammasome inhibition in prostate cancer using animal models, clinical studies are required to understand its role in the progression of prostate cancer." (PMID 39769450, 2024). "NLRP3 inflammasome activation in prostate cancer cells can enhance tumor cell growth, survival, migration, and invasion by regulating autophagy, mitochondrial metabolism, and epithelial-mesenchymal transition." (PMID 37715239, 2023). "In contrast, in high NLRP3-expressed cancer cells, such as prostate cancer cell line PC3, the secretion of VEGF and MMP-13 was higher compared to MCF-7 cells." (PMID 36902278, 2023). "New insights have been provided into the mechanisms of NLRP3 inflammasome as a potential target for the treatment of prostate cancer (PCa)." (PMID 37891577, 2023). "Prostate cancer derived-EVs, by inducing NLRP3 activation and IL-1β maturation, modify the inflammatory response of ME residing cells in a tumor-promoting fashion." (PMID 35530309, 2022). "The protein level of NLRP3 in prostate cancer cell lines was variable and corroborated with the expression pattern of mRNA and IHC." (PMID 28663562, 2017). "Specifically, in vitro studies could focus on measuring NLRP3 expression and activation in response to DNA damage induced by agents like cisplatin or radiation in ovarian and prostate cancer cell lines." (PMID 40718836, 2025). "The NLRP3 inflammasome may exert protective effects on prostate cancer by modulating the tumor microenvironment and immune response." (PMID 40718836, 2025).
prostate carcinoma (continued). "Since IL-18 and IL-1β are produced in large quantities during NLRP3 inflammasome activation, current findings indicate that the NLRP3 inflammasome and its downstream pathways may promote prostate cancer progression." (PMID 40718836, 2025). "Moreover, the study lacked functional validation, subgroup analysis by tumor grade or stage, and assessment of cytokine output, which limits its ability to capture the dynamic pro- or anti-tumor role of NLRP3 in prostate cancer." (PMID 40718836, 2025). "In support of this, the molecular mechanism by which the overactivation of the NLRP3 inflammasome promotes the malignant progression of prostate cancer has been defined, proposing this inflammasome as a new prognostic biomarker and potential therapeutic target for this cancer." (PMID 38791274, 2024). "Finally, by extending the differential expression analysis to other tissues, we found that in the pancreas, colon, prostate cancers, and more widely pan-cancers, NLRP3 expression was also significantly lower." (PMID 36746533, 2023). "NLRP3 inflammasome is a key regulator of inflammation in prostate cancer." (PMID 37715239, 2023). "These include ATP, which can activate NLRP3 inflammasome via the purinergic P2 × 7 receptors and, specifically in prostate tissue, uric acid, crystals, and infections, which have all been involved in prostate cancer progression." (PMID 34070682, 2021). "A previous study showed that NLRP3 was upregulated in prostate cancer cells, and hypoxia could contribute to prostatic chronic inflammation and activate the NLRP3 inflammasome." (PMID 28865486, 2017). "Moreover, K+ efflux, one of the activation pathways of the NLRP3 inflammasome, has been identified as an early event in the apoptosis of prostate cancer cells, suggesting that the NLRP3 inflammasome may induce tumor cell apoptosis through this mechanism." (PMID 40718836, 2025). "Similarly, NLRP3 acetylation and inhibition of inflammasome complex formation by androgen receptor inhibitor could block prostate cancer progression in nude-mice xenografts." (PMID 39769450, 2024). "Therefore, targeting NLRP3 inflammasome or its downstream effectors may represent a promising therapeutic approach to inhibit inflammation and improve immunotherapy in prostate cancer." (PMID 37715239, 2023). "Using Gene Expression Omnibus (GEO) public datasets, we screened the expression profiles of inflammasome sensors NLRP3, NLRC4, NLRP6, NRLP12, and AIM2 in prostate tumor tissues, and verified their mRNA level in a panel of prostate cancer cell lines." (PMID 28663562, 2017). "Further, hypoxia potentiated activation of the NLRP3 and AIM2 inflammasome in prostate epithelial, prostate cancer, and THP-1 cell lines." (PMID 27058421, 2016). "Carvedilol (CVL), a β-adrenergic receptor antagonist, promotes NF-κB nuclear translocation through the NLRP3-caspase-1-ASC inflammasome, inducing pyroptosis in prostate cancer (PCa) cells and establishing a foundation for the application of β-adrenergic antagonists in PCa treatment." (PMID 40718836, 2025). "We found that the advanced stage prostate cancer PC3 cells, exhibit comparable NLRP3 protein expression level but higher pro-IL-1β and active P-20 fragment of caspase-1, paralleled by doubled IL-1β secretion level after 48 h of culture compared to the androgen-sensitive LNCaP cells." (PMID 34070682, 2021). "To verify whether NPs can exert the same effects in prostate cancer PC3 cells, we analyzed the effect of 1 μM ANP or BNP treatment for 24 h on Ser295 phosphorylation of NLRP3 in PC3 cells." (PMID 34070682, 2021). "When compared to other cancers, the role of NLRP3 in prostate cancer is not well investigated." (PMID 39769450, 2024). "Furthermore, NPs are able to counteract both the constitutive and EVs-induced NLRP3 activation in cancerous and non-cancerous prostate cells, supporting the critical role of these molecules in prostate cancer." (PMID 35530309, 2022).
prostate carcinoma (continued). "We recently demonstrated that EVs secreted by prostate cancer PC3 cell line (PC3-EVs) could induce NLRP3 inflammasome activation in non-cancerous PNT2 prostate cells, thus supporting the tumor-promoting microenvironment." (PMID 34070682, 2021). "We found that the mRNA level was very much variable across the cell lines, and there was no consensus on the expression levels of NLRP3, NLRC4, NLRP6, and AIM2 among early stage (e.g. LNCaP and LNCaP-Ln3) and late stage (e.g. PC3 and DU145) prostate cancer cell lines." (PMID 28663562, 2017).
AIDS (22 papers, 2009 to 2026). A syndrome resulting from the acquired deficiency of cellular immunity caused by the human immunodeficiency virus (HIV). "NLRP3-associated autoinflammatory diseases (NLRP3-AIDs) are rare autoinflammatory disorders caused by uncontrolled inflammasome activation." (PMID 41898699, 2026). "There are numerous NLRP3 mutations that cause NLRP3-associated autoinflammatory diseases (NLRP3-AIDs), mostly in or around the NACHT domain." (PMID 34671876, 2022). "Cryopyrin‐associated periodic syndromes also known as NLRP3‐associated autoinflammatory diseases (NLRP3‐AIDs) comprise a series of rare monogenic autoinflammatory conditions which range in severity from the mildest FCAS, to the moderate Muckle–Wells syndrome (MWS), and more severe CINCA/NOMID." (PMID 35832835, 2022). "Targeting CD177 represents a superior therapeutic strategy for NLRP3-AIDs, including IL-1β-refractory cases." (PMID 41898699, 2026). "IL-1β and IL-18, potent pro-inflammatory cytokines and primary outputs of the activated NLRP3 inflammasome, play crucial roles in the development of various inflammatory and AIDs." (PMID 38666950, 2024). "While effective in managing NLRP3-driven inflammatory diseases and AIDs, the use of IL-1 blockade remains limited, partly due to frequent injections and the potential infection risks." (PMID 38666950, 2024). "Hearing loss and autoinflammatory symptoms were generally reversed or improved following treatment with the interleukin-1 (IL-1) receptor antagonist anakinra, which has been historically used in the treatment of NLRP3-AIDs." (PMID 34671876, 2022). "NLRP3-AIDs are typified by recurrent episodes of fever, urticaria, arthralgia, and chronic inflammation which can lead to long-term damage including sensorineural hearing loss and amyloidosis." (PMID 34671876, 2022). "Our results highlight the importance of investigating alternative pathways involved in disease states and outline a potential course of treatment for atypical NLRP3-AIDs patients." (PMID 34671876, 2022). "Though NLRP3 is the common denominator of all NLRP3-AIDs, the differences in clinical manifestations and disease onset distinguish them from each other." (PMID 33329557, 2020). "This study demonstrates that NLRP3 SNPs are associated with HIV-1 infection and AIDS progression." (PMID 40331958, 2025). "Multiple studies have indicated that somatic mutations in immune cells could contribute to AIDs, including CAPS (caused by NLRP3 variants) and TNF receptor-associated periodic syndrome (caused by TNFRSF1A variants)." (PMID 41168503, 2025). "NLR family pyrin domain containing 3 (NLRP3)–associated autoinflammatory disease (NLRP3-AID), formerly known as cryopyrin-associated periodic syndrome, is a group of AIDs comprising neonatal-onset multisystem inflammatory disorder, Muckle–Wells syndrome, and familial cold autoinflammatory syndrome." (PMID 40852416, 2025). "Similarly, individuals with the CC genotype at NLRP3 rs10754558 showed a later AIDS clinical stage compared to those with the GC and GG genotypes (p = 0.027, OR = 1.532, 95% CI 1.048–2.239)." (PMID 40331958, 2025). "However, IL-6 was significantly raised in the patient’s serum, as previously observed in different NLRP3-AIDs." (PMID 34671876, 2022). "This meta-analysis suggests that the NLRP3 rs10754558, but not rs35829419, polymorphism is associated with susceptibility to AIDs, especially in Latin American individuals." (PMID 34367252, 2021). "Moreover, flares of NLRP3-related AIDs were documented after the pneumococcal vaccine." (PMID 36275663, 2022). "NLRP3 (previously known as CIAS1) is part of the CATERPILLER (CARD (caspase recruitment domain), Transcription Enhancer, R (purine)-binding, Pyrin, Lots of Leucine Repeats) gene family and mutations in some of these genes have been shown to result in severe auto-inflammatory diseases (AIDs)." (PMID 19784369, 2009).
AIDS (continued). "Three SNPs (OAS1 rs1131454, NLRP3 rs10754558, and MAVS rs867335) were found to be related to the clinical staging of AIDS." (PMID 40331958, 2025).
HIV-1 infection (22 papers, 2013 to 2025). The type species of lentivirus and the etiologic agent of acquired immunodeficiency syndrome (AIDS). "The activation of the NLRP3 inflammasome in HIV-1 infection is caused by multiple mechanisms, including potassium efflux, mitochondrial release of reactive oxygen species, and lysosomal damage." (PMID 40331958, 2025). "Our findings reveal that individuals with genotypes TT and TC at NLRP3 rs4612666 are more susceptible to HIV-1 infection than those with the CC genotype." (PMID 40331958, 2025). "At NLRP3 rs4612666, individuals with the TT and TC genotypes had a higher risk of HIV-1 infection compared to those with the CC genotype (p = 0.040, OR = 1.325, 95% CI 1.012–1.733)." (PMID 40331958, 2025). "As previously reviewed by our group, cannabis use is largely associated with protective effects against inflammation in PWH, and CB2R signaling has been linked to reduced HIV-1 infection and NLRP3 inflammasome activation." (PMID 39529883, 2024). "Further suggesting a role for NLRP3 for control of HIV-1 infection, polymorphisms in genes for NLRP3 and the inflammatory cytokine IL-1β are both associated with increased susceptibility to HIV-1 infection." (PMID 23435233, 2013). "And it has been reported that single nucleotide polymorphisms (SNPs) in the 3’-untranslated region (3’-UTR) of NLRP3 gene may be associated with susceptibility to HIV-1 infection." (PMID 37465759, 2023). "The findings that cannabinoid treatment and CB2R activation are associated with reduced HIV-1 infection and inflammation and with reduced NLRP3 inflammasome signaling suggest a link between HIV-1 disease, CB2R receptor signaling, and NLRP3 inflammasome activation." (PMID 37027347, 2023). "The results revealed significant association between five SNPs (NLRP3 rs4612666, MAVS rs17857295, MAVS rs6084497, MAVS rs16989000, and JAK1 rs4244165) and HIV-1 infection." (PMID 40331958, 2025). "An investigation into single nucleotide polymorphisms (SNPs) within NLRP1, NLRP3, NLRC4, CARD8, CASP1, and IL1B genes revealed a significant association between two SNPs residing in NLRP3 and IL1B with increased susceptibility to HIV-1 infection." (PMID 38785555, 2024). "This study sought to uncover the synergistic effects of HIV-1 infection and nicotine on immune cell function, focusing on beneficial insights into NLRP3 inflammasome activation, oxidative stress, and mitochondrial pathways." (PMID 39599911, 2024). "Except for NLRP3 and PYHIN, which were reported more frequently, NLRP1, NLRC4 and NLRC5 inflammasome can also be activated by HIV-1 and are closely associated with HIV-1 infection." (PMID 37465759, 2023). "HIV-1 infection can induce inflammasome activation as intermediary products are recruited by the DNA sensor IFI16 to signal through NLRP3 with an additional signal such as toll-like receptor activation." (PMID 37027347, 2023). "We confirmed that HIV-1 infection significantly induced NLRP3 in HTOC CD4+ T cells expanding in the presence of ARI." (PMID 36693889, 2023). "Expression of caspase-1, NLRP3, and IL-1β was increased in lymph nodes and bone marrow between day 1 and 3 after HIV-1 infection (mean fold change (FC) of 2.08, 3.23, and 6.05, p<0.001, respectively)." (PMID 36800238, 2023). "Specifically, HIV-1 infection induces NLRP3 inflammasome activation and stimulated secretion of pro-inflammatory cytokines including Interleukin-1β." (PMID 34067600, 2021). "Other studies in human monocytes have shown that HIV-1 infection-induced production of IL1β via the NLRP3 inflammasome-dependent mechanism(s)." (PMID 32784383, 2020). "The NLRP3 inflammasome pathway is activated in HIV-1 infection contributing to chronic inflammation and has also been implicated in atherosclerotic plaque formation." (PMID 32596261, 2020). "Together these studies provide evidence for the role of the NLRP3 inflammasome during HIV-1 infection." (PMID 32784383, 2020).